NOTCH1 (notch receptor 1)
Diseases named in the same sentence as NOTCH1 in open-access papers (continued):
Sharing a sentence is not in itself a finding about the gene and the disease.
lung cancer (continued). "Apart from the PI3K/AKT pathway, CNTN1 is also associated with the RhoA pathway in gastric cancer; VEGF-C/VEGFR-3 pathway in lung, gastric, and esophageal cancers, and OSCC; α7 nAChR/ERK and Src-p38 MAPK-C/EBPα pathways in lung cancer; and Notch1 and RET/PTC3 pathways in thyroid cancer." (PMID 33194679, 2020). "On the other hand, when Notch1 was ablated in parental lung carcinoma cells, EMT was inhibited." (PMID 30917608, 2019). "Nevertheless, few studies focus on the association between mutations in Notch1 and lung cancer, especially non-smoking female lung cancer." (PMID 28415716, 2017). "Notch1 activation can also enhance epithelial-mesenchymal transition (EMT) in lung cancer cells." (PMID 28061457, 2017). "Similarly to galectin-3, galectin-1 has recently been identified to promote lung cancer metastasis by potentiating integrin α6β4 and Notch1/Jagged2 signaling." (PMID 28860622, 2017). "In human lung tumors, miR-494-3p is highly expressed at the invasive front and its forced expression in lung cancer cells induces a stem-like phenotype, with increased side population compartment, tumor sphere formation, heightened cell motility, and increased NOTCH1 signaling." (PMID 27980227, 2017). "Here we explored the relationship of three SNPs (rs3124599, rs3124607 and rs3124594) in Notch1 with the risk and the survival of lung cancer in non-smoking females, including 556 cases and 395 controls." (PMID 28415716, 2017). "The results suggested that polymorphism of rs3124599 in Notch1 was associated with the risk of lung cancer in non-smoking females, especially with the risk of SCLC." (PMID 28415716, 2017). "In the current study, we estimated the relationship between three SNPs in Notch1 and the risk of lung cancer among 951 non-smoking females, including 556 cases and 395 controls." (PMID 28415716, 2017). "In conclusion, our study focused on the relationship between polymorphisms in Notch1 and the susceptibility and survival of lung cancer in non-smoking females in the northeast of China." (PMID 28415716, 2017). "In conclusion, molecular characterization of EpCAM+ CTCs from advanced NSCLC patients provided with highly specific biomarkers with potential applicability as a “liquid biopsy” for monitoring of NSCLC patients and confirmed NOTCH1 as a potential therapeutic target to block lung cancer dissemination." (PMID 27901069, 2016). "Further, analyses of human lung cancers from 30 patients showed that HO-1 is negatively correlated with P-Erk1/2 in the stroma tissues indicating the possible implication of HO-1 in the effects of CO on P-Erk1/2 and Notch1 signaling." (PMID 26993595, 2016). "There was a reciprocal regulation between EZH2 and NOTCH1 in lung cancer cells." (PMID 27049834, 2016). "Interestingly, endothelial cells were also showed to play a tumor-inhibitory effect on lung cancer growth by Dll4/Notch1/PTEN signaling pathway." (PMID 27215466, 2016). "Overall, our current understanding of the role of NOTCH1 in lung cancer is still incomplete." (PMID 26491213, 2015). "Notch-1 was actively involved in promoting the metastasis of esophageal carcinoma cells by inducing EMT and its activation was also implicated in potentiating EMT of gefitinib-resistant lung cancer cells." (PMID 25990317, 2015). "Conversely, in the murine model of Notch1-induced lung cancer, Sox9 is overexpressed as early as 7 days after induction of Notch1 overexpression in the alveolar epithelium, specifically confined to the alveolar hyperplastic regions, and thus is likely to be directly downstream of Notch." (PMID 25004243, 2014). "Notch1 and 3 are considered to have a relatively close correlation with lung cancer." (PMID 23420695, 2013). "Notch1 are over-expressed in a variety of cancers, including lung cancer." (PMID 23651443, 2013). "Our results suggest that CK2 is a positive regulator in Notch1 signalling in human lung cancer." (PMID 23651443, 2013).
lung cancer (continued). "Our data suggest that CK2α inhibitors may be beneficial to the lung cancer patients with activated Notch1 signalling." (PMID 23651443, 2013). "Thus, we report that the inhibition of CK2α down-regulates Notch1 signalling and subsequently reduces a cancer stem-like cell population in human lung cancer cells." (PMID 23651443, 2013). "Less is known about NOTCH1 in lung cancer cases with radiation exposure." (PMID 23028920, 2012). "Thus, we investigated whether BAI1 signaling, which facilitates apoptotic lung cancer cell uptake, influences Notch1 signaling in CAFs." (PMID 36241874, 2022). "We tested whether Notch1/TAZ axis regulates lung cancer cell proliferation in cultured cells." (PMID 34482375, 2021). "Thus, targeting Notch1 and TAZ may make lung cancer therapy more effective than targeting Notch1 or TAZ alone." (PMID 34482375, 2021). "The interaction between Notch1 and TAZ has been shown to promote aerobic glycolysis and facilitate immune evasion in lung cancer." (PMID 41203613, 2025). "As a core pathway in lung injury repair, Notch1/3 is highly expressed in COPD, pulmonary hypertension, and lung cancer, driving disease progression." (PMID 41012354, 2025). "To date, the role of GATAD2B in those NOTCH1-addicted cancers is unclear, although GATAD2B has been identified as a metastatic driver in lung cancer." (PMID 38043798, 2024). "CHRNA5 accelerates lung cancer progression via the MAPK and VEGF pathways, influences melanoma growth via Notch1 regulation, and promotes radioresistance in oral squamous cell carcinoma by modulating E2F transcription factors." (PMID 38840910, 2024). "It is worth noting that MIB2 is reported to be a suppressor in lung cancer, which discover that MIB2 inhibits the proliferation, migration, and invasion of non-small cell lung cancer through ubiquitination of Notch1." (PMID 37436668, 2023). "PNO1/CRISPR/Cas9 inhibited the expression of Notch1, Notch2, Notch3 Jagged1, and DLL1 in lung cancer A549 and H460 cells." (PMID 36625087, 2023). "In the present study, we found that the BAI1/Rac1 signaling pathway positively controls Notch1 signaling, leading to WISP-1 secretion from and efferocytosis of apoptotic lung cancer cells by CAFs." (PMID 36241874, 2022). "To further validate our experimental results, we examined the clinical significance of Notch1 and EMCN in lung cancer by analyzing TCGA dataset." (PMID 36184589, 2022). "Here we report a positive feedback loop of Notch1 and TAZ in lung cancer cells that increases lactate production, which promotes immune escape." (PMID 34482375, 2021). "Increased level of extracellular lactate via Notch1/TAZ axis inhibited cytotoxic T-cell activity, leading to the invasive characteristic of lung cancer cells." (PMID 34482375, 2021). "In conclusion, our study indicates that interaction between Notch1 and TAZ promotes aerobic glycolysis and immune escape in lung cancer." (PMID 34482375, 2021). "Our findings provide potential therapeutic targets against Notch1 and TAZ and would be important for clinical translation in lung cancer." (PMID 34482375, 2021). "In fact, the tumour‐promoting role of NOTCH1 in NSCLC development has been well documented, and NOTCH1 inhibitors have been tested in preclinical studies of lung cancer." (PMID 33237585, 2021). "Together the results suggest that interaction between Notch1 and TAZ promotes aerobic glycolysis and immune escape in lung cancer." (PMID 34482375, 2021). "In a subset of lung cancer cells, Gefitinib-resistant cells displayed an EMT phenotype as well as an increase in Notch1 expression, when compared to their parental cells." (PMID 30917608, 2019). "Our investigation is the first to extensively explore the relationship between curcumin and EZH2 in lung cancer cells and the reciprocal regulation between EZH2 and NOTCH1." (PMID 27049834, 2016).
lung cancer (continued). "Several studies have demonstrated that miR-34a retards lung cancer cell growth or induces apoptosis by targeting TGFβR2, Axl, Notch-1, or HDM4, whereas miR-497 does so by targeting HDGF in lung cancer." (PMID 25909221, 2015). "Our results thus far demonstrate that SOX2 regulates the transcriptional network of oncogenes, including WNT1, WNT2, NOTCH1 and c-MYC and promotes the tumorigenesis of human lung cancer cells." (PMID 22615765, 2012). "In hypoxic lung cancer cells, hypoxia leads to increased expression of Notch1 through a HIF-1α–dependent induction of Notch1 mRNA." (PMID 22363487, 2012). "We observed an up-regulation of cancer-related proteins, including NOTCH1, with increasing cumulative exposure to radon or arsenic, but could not detect an additional effect of exposure on the very distinct patterns of proteins of the major subtypes of lung cancer." (PMID 23028920, 2012). "To better understand resistant cancer cell heterogeneity, we isolated a novel riboflavin+NOTCH1+ population from cisplatin-naïve and -resistant lung cancer cell lines and patient specimens with or without immunotherapy and chemotherapy." (PMID 41453945, 2025). "Taken together, riboflavin+NOTCH1+ cells represent a resistant population in lung cancer cell lines and specimens regardless of immunotherapy and chemotherapy." (PMID 41453945, 2025). "Accordingly, to describe Notch1-related effects in SCLC, it is essential to build thorough knowledge about Notch1 and its related protein expression (Hes1, c-Myc, and Jagged1) in various lung cancer cell lines." (PMID 40034926, 2024). "Further, HDAC5 displays a significant upregulation in lung cancer and increases the proliferation and invasion of lung cancer cells through the upregulation of DLL4 (Delta-like protein 4), Notch-1 (Neurogenic locus notch homolog protein 1) and Twist-1 (Twist-related protein 1)." (PMID 35626663, 2022). "In line with the role of Notch1 in stimulating effector T-cell functions, exogenous expression of Notch1 in CD8+ T-cells enhances anti-cancer T-cells responses and render T-cells resistant to immunosuppression in the tumor microenvironment of lung carcinoma and thymoma." (PMID 36090975, 2022). "Accordingly, our results show that TAZ promotes the expression of Notch1 and Notch1 stabilizes TAZ protein, indicating a potent positive feedback loop between TAZ and Notch signaling in lung cancer that may orchestrate aerobic glycolysis." (PMID 34482375, 2021). "The results suggest that increased levels of extracellular lactate via Notch1/TAZ axis inhibits cytotoxic T-cell activity and the activation of tumor infiltrated NK cells, which may contribute to the invasive nature of lung cancer cells." (PMID 34482375, 2021). "Interaction between Notch1 and TAZ promoted aerobic glycolysis and immune escape in lung cancer." (PMID 34482375, 2021). "In lung cancer, VEGF directly affects expression of Dll4 in tumor vessels, as well as in neuroblastoma models, where blocking VEGFR2 increases the level of Jagged1 expression and consequent Notch1 hyperactivation." (PMID 30917608, 2019). "It has been reported that cisplatin treatment enriches NOTCH1 and CD133-expressing lung cancer stem-like cells from H460 and H661, induce DNA damage responses, and upregulate ABC drug transporters which in turn, increases cross-resistance to other chemotherapeutics (doxorubicin and paclitaxel)." (PMID 30464927, 2018). "To understand the functional biology of NOTCH1 in lung cancer cells, we knocked down the expression of NOTCH1 using siRNA." (PMID 27049834, 2016).
lung cancer (continued). "In conclusion, curcumin inhibits lung cancer growth through, at least in part, the inhibition of EZH2 and its reciprocally regulated molecule NOTCH1, suggesting that the molecules that are involved in the EZH2/NOTCH signaling pathway are potential therapeutic targets for lung cancer." (PMID 27049834, 2016). "However, miR-200c significantly repressed endogenous NOTCH1 expression in multiple lung cancer cells, suggesting that the regulation of NOTCH1 3′-UTR by miR-200c was critical for endogenous NOTCH1 expression." (PMID 27456471, 2016). "The biologic basis for the distinct actions of NOTCH1 in regulating lung cancer cell growth is not well understood." (PMID 26491213, 2015). "Together, the results identify a new functional role for a Notch1-Sox9 signaling axis in lung ADC that may explain the correlation of Sox9 with tumor progression, higher tumor grade, and poor lung cancer survival." (PMID 25004243, 2014). "In addition, SIRT1 negatively regulated the activity of Notch1 signaling in endothelium of lung cancer and inhibited N1IC expression which leading to endothelial cell proliferation and promoting the growth of lung cancer." (PMID 25420528, 2014). "However, on the other hand, inactivating NOTCH1 or ADAM17 resulted in substantial cell death, while EGFR inhibition predominantly induced cell arrest in lung cancer." (PMID 22239941, 2012). "ERBB2 and NOTCH1 showed an up-regulation in lung-cancer tissue with increased exposure to both carcinogens, but no staining or a lacking association with exposure in cancer-free samples." (PMID 23028920, 2012). "In many types of cancer, including pancreatic, colon, nonsmall cell lung cancer (NSCLC), cervical and renal cell cancer, Notch1 is upregulated; furthermore, it has been suggested that expression of Notch1 signaling prevents cellular differentiation and inhibits apoptosis in these cancer types." (PMID 20069043, 2009). "Thus, we hypothesized that Notch1-WISP-1 signaling induced by ApoSQ plays a crucial role in the antimigratory and anti-invasive effects on lung cancer cells and CAFs." (PMID 36241874, 2022). "Taken together, these data suggest that conditional Notch1 deficiency in this autochthonous KrasLSL-G12V driven lung cancer mouse model induces papillary ADCs accompanied by SPC+ tumor cell accumulation inside the bronchiolar lumen, which is not found under Notch1 wild-type conditions." (PMID 34257546, 2021). "Our results showed that ZEB1 promoted NOTCH1 but not Jagged1 in lung cancer cells, suggesting that the ZEB1/miR-200 axis may regulate NOTCH signalling through differential mechanisms in different types of human cancer cells." (PMID 27456471, 2016). "An analysis of NOTCH1 and HES1 gene expression and Notch intracellular domain (NICD) nuclear translocation during DLK1 stimulation or depletion demonstrated that DLK1 could activate Notch signaling in lung cancer cells." (PMID 24621612, 2014). "In addition, higher expression of the oncogenes c-MYC, WNT1, WNT2 and NOTCH1 was detected in side population (SP) cells than in non-side population (NSP) cells of A549 lung cancer cells, indicating a possible mechanism for the tumorigenic potential of CSC’s." (PMID 23349823, 2013). "Our findings indicate that the inactivation of NOTCH1 alone, without concomitant inhibition of EGFR, may lead to unexpected outcomes in lung cancer by increasing ERBB3 to promote EGFR-mutated tumour growth, providing a caution against indiscriminate use of NOTCH inhibitors." (PMID 27456471, 2016). "However, neither curcumin nor RNAi against EZH2 or NOTCH1 could induce cell apoptosis in the lung cancer cells that we investigated." (PMID 27049834, 2016).
lung cancer (continued). "Thus, despite reports of NOTCH1 PEST domain mutations in lung cancer and NOTCH3 amplification and acquired mutations in genes encoding other NOTCH pathway signaling components in ovarian cancer, NOTCH1 activation does not appear to be common in either of these tumors." (PMID 23825651, 2013). "Thus, we hypothesized that, in addition to Notch1, novel SIRT1-regulated transcription factors may also be involved in vascular development, although future studies are required to address the role of these unknown regulators in lung cancer." (PMID 23028940, 2012). "Nevertheless, it should be noted that the inhibition of NOTCH1 by γ-secretase inhibitor treatment or by siRNAs also significantly promoted both ERBB3 expression and lung cancer cell growth in the absence of gefitinib." (PMID 27456471, 2016). "In future studies, it would be interesting to examine whether NOTCH1 has distinct or differential roles in lung adenocarcinoma cells that harbor other gene mutations, especially the mutations that do not coexist with KRAS mutations in lung cancer cells, for instance, EGFR mutations." (PMID 26491213, 2015).